PRKCI (protein kinase C iota)
Description:
Calcium- and diacylglycerol-independent serine/ threonine-protein kinase that plays a general protective role against apoptotic stimuli, is involved in NF-kappa-B activation, cell survival, differentiation and polarity, and contributes to the regulation of microtubule dynamics in the early secretory pathway. Is necessary for BCR-ABL oncogene-mediated resistance to apoptotic drug in leukemia cells, protecting leukemia cells against drug-induced apoptosis. In cultured neurons, prevents amyloid beta protein-induced apoptosis by interrupting cell death process at a very early step. In glioblastoma cells, may function downstream of phosphatidylinositol 3-kinase (PI(3)K) and PDPK1 in the promotion of cell survival by phosphorylating and inhibiting the pro-apoptotic factor BAD. Can form a protein complex in non-small cell lung cancer (NSCLC) cells with PARD6A and ECT2 and regulate ECT2 oncogenic activity by phosphorylation, which in turn promotes transformed growth and invasion. In response to nerve growth factor (NGF), acts downstream of SRC to phosphorylate and activate IRAK1, allowing the subsequent activation of NF-kappa-B and neuronal cell survival. Functions in the organization of the apical domain in epithelial cells by phosphorylating EZR. This step is crucial for activation and normal distribution of EZR at the early stages of intestinal epithelial cell differentiation. Forms a protein complex with LLGL1 and PARD6B independently of PARD3 to regulate epithelial cell polarity. Plays a role in microtubule dynamics in the early secretory pathway through interaction with RAB2A and GAPDH and recruitment to vesicular tubular clusters (VTCs). In human coronary artery endothelial cells (HCAEC), is activated by saturated fatty acids and mediates lipid-induced apoptosis. Involved in early synaptic long term potentiation phase in CA1 hippocampal cells and short term memory formation (By similarity).
Synonyms: DXS1179E; PKCI; nPKC-iota
Tractability: Small molecule: an approved drug acts on it; a structure with a bound ligand is known; a high-quality ligand is known; it has a high-quality binding pocket; it belongs to a druggable protein family. Antibody: its Gene Ontology location is reachable by antibodies, with high confidence. PROTAC: it is named in the literature on targeted protein degradation; ubiquitination databases record sites on it; its protein half-life has been measured; a small molecule that binds it is known.
Target class: AGC protein kinase PKC iota subfamily; AGC protein kinase group; Protein Kinase; AGC protein kinase PKC family; Kinase; Enzyme
Chemical probes: PD134384, PD134385, PD134386, PKCiota-IN-2
Gene: Protein-coding gene on chromosome 3 (170,222,124 to 170,305,978, forward strand). Ensembl gene ENSG00000163558.
Subcellular location: Cytoplasm; Membrane; Endosome; Nucleus
Subcellular location (Human Protein Atlas): Cytosol; Cytokinetic bridge; Microtubules; Primary cilium
Pathways (Reactome):
Signal Transduction: Pre-NOTCH Transcription and Translation; p75NTR recruits signalling complexes
Cell-Cell communication: Tight junction interactions
Cellular responses to stimuli: KEAP1-NFE2L2 pathway
Gene Ontology:
Molecular function: phospholipid binding; protein binding; protein kinase activity; protein serine/threonine kinase activity; ATP binding; diacylglycerol-dependent, calcium-independent serine/threonine kinase activity; diacylglycerol-dependent serine/threonine kinase activity; protein serine kinase activity
Biological process: cell-cell junction organization; establishment or maintenance of epithelial cell apical/basal polarity; negative regulation of glial cell apoptotic process; negative regulation of neuron apoptotic process; positive regulation of endothelial cell apoptotic process; positive regulation of glial cell proliferation; positive regulation of neuron projection development; protein phosphorylation; cellular response to chemical stress; cellular response to insulin stimulus; cytoskeleton organization; establishment of cell polarity; intracellular signal transduction; membrane organization; negative regulation of apoptotic process; positive regulation of D-glucose import; positive regulation of Notch signaling pathway; positive regulation of protein localization to plasma membrane; protein localization to plasma membrane; protein targeting to membrane; secretion; vesicle-mediated transport; cell migration; Golgi vesicle budding; regulation of postsynaptic membrane neurotransmitter receptor levels; and 2 more
Cellular component: cytoplasm; cytosol; endosome; extracellular exosome; membrane; nucleus; PAR polarity complex; nucleoplasm; plasma membrane; tight junction; apical part of cell; apical plasma membrane; bicellular tight junction; brush border; cell leading edge; glutamatergic synapse; Golgi membrane; Schaffer collateral - CA1 synapse; Schmidt-Lanterman incisure
Genetic constraint (gnomAD): Loss-of-function variants: 24 observed, 50.96 expected, observed/expected ratio (o/e) 0.47, 90% interval 0.34 to 0.66. The upper end of that interval is the gene's LOEUF score, 0.66, which puts it in group 2 of 6, group 1 being the genes least tolerant of losing a copy. Missense variants: 338 observed, 531.69 expected, observed/expected ratio (o/e) 0.64, 90% interval 0.58 to 0.7. Synonymous variants: 146 observed, 166.34 expected, observed/expected ratio (o/e) 0.88, 90% interval 0.77 to 1.01.
Homologues: Orthologues: chimpanzee PRKCI (100% identical), macaque PRKCI (99% identical), rabbit PRKCI (99% identical), rat Prkci (99% identical), dog PRKCI (98% identical), mouse Prkci (98% identical), pig PRKCI (95% identical), tropical clawed frog prkci (91% identical), zebrafish prkci (88% identical), Caenorhabditis elegans tpa-1 (35% identical), Drosophila melanogaster Pkcdelta (33% identical), Drosophila melanogaster Pkc53E (33% identical), and 4 more. Paralogues in human: PRKCZ (71% identical), PRKCE (39% identical), PRKCH (38% identical), PRKCA (36% identical), PRKCB (36% identical), PRKCG (34% identical), PKN2 (33% identical), PKN1 (30% identical), PKN3 (30% identical).
Diseases named in the same sentence as PRKCI in open-access papers:
PRKCI is named in the same sentence as 60 diseases in open-access papers, as found by Europe PMC text mining. Sharing a sentence is not in itself a finding about the gene and the disease. The quoted sentences say what the papers report.
ovarian carcinoma (17 papers, 2009 to 2025). A malignant neoplasm originating from the surface ovarian epithelium. "PRKCI (encodes protein kinase C, iota) is overexpressed in ovarian cancer and was suggested to promote immune suppression." (PMID 31426369, 2019). "It is believed that PRKCI can be used as a therapeutic target for ovarian cancer based on gene overexpression and immunosuppression in ovarian cancer." (PMID 39015499, 2024). "PRKCI, in contrast, increased myeloid-derived suppressor cells and decreased cytotoxic T-cell infiltration in ovarian cancer, leading to an immune-suppressive TME." (PMID 35174160, 2021). "In the study of gynecological tumors, the expression of PRKCI in ovarian cancer tissues was significantly higher than it was in normal tissues, and it enhances the invasion and proliferation ability of ovarian cancer cells." (PMID 32993576, 2020). "PRKCI likely inhibits the recruitment of immune cells in the microenvironment of ovarian cancer by regulating the activity of YAP1 through the Hippo signaling pathway, resulting in immunosuppression and promoting tumor growth." (PMID 32993576, 2020). "As a member of the protein kinase C family, PRKCI affects tumorigenesis, progression and chemosensitivity by regulating the Wnt/beta-catenin pathway and immune microenvironment in lung cancer, ovarian cancer and alveolar rhabdomyosarcoma." (PMID 33234130, 2020). "YAP has further been found to function downstream of the ovarian cancer-specific oncogene PRKCI (protein kinase C iota) to up-regulate TNF (tumor necrosis factor) expression, recruiting MDSC to inhibit cytotoxic T cell functions." (PMID 31052239, 2019). "The biological significance of PRKCI in CCOC is further suggested by the distinctive molecular context of this ovarian cancer subtype." (PMID 29228547, 2017). "The role of PRKCI in these cellular processes has led to its use as a prognostic marker and therapeutic target in non-small cell lung and ovarian cancer." (PMID 20686607, 2010). "For example, while the PIK3CA gene was selected from the 3q26 amplicon as the oncogene for subsequent functional analysis, the PRKCI gene from the same region was proposed by a different group to be the oncogene in ovarian cancer." (PMID 19419571, 2009). "In addition to PRKCZ, it is also important to note the potential roles of PRKCI (protein kinase C iota) in ovarian cancer." (PMID 25874946, 2015). "In ovarian cancer, YAP activation impairs NK cell infiltration by enhancing MDSC recruitment through protein kinase C iota (PRKCι)-dependent signaling." (PMID 41028521, 2025). "Several protein kinases within this amplicon have been characterized as genetic drivers in different malignancies, including PKCι (PRKCI) in NSCLC and ovarian cancer, or LZK (MAP3K13) in HNSCC." (PMID 31817861, 2019).
lung carcinoma (6 papers, 2009 to 2024). "Other studies believe that PRKCI is an oncogene of lung cancer and is essential to maintaining the transformed phenotype of human nonsmall cell lung cancer cells." (PMID 39015499, 2024). "PRKCI was shown to be required for the maintenance of a tumorigenic phenotype in lung cancer cells possessing PRKCI amplification and in LSQCC." (PMID 30060526, 2018). "Genetic disruption of PRKCI in the LSL-KRASG12D mouse LAC model inhibits tumor initiation by blocking the expression of lung cancer initiating cells." (PMID 30060526, 2018). "PRKCI is also considered as an oncogene activated by nicotine and a critical gene in lung cancer development, conferring cell survival, drug resistance, migration and invasion." (PMID 19662092, 2009).
lung squamous cell carcinoma (6 papers, 2014 to 2024). "For example, most (> 90%) of LSCC (Lung Squamous Cell Carcinoma) tumors exhibit an increase in copy number at chromosome 3q26, resulting in the upregulation of the PRKCI, SOX2, and ECT2 oncogenes and LSCC tumorigenesis." (PMID 38504159, 2024). "It has recently been shown that co-amplification of SOX2 and PRKCI contributes to the aggressive behavior of lung squamous cell carcinoma, by promoting a stem-like phenotype through activation of the Hedgehog signaling." (PMID 25300947, 2014). "The co-amplification of FXR1, protein kinase C, iota (PRKCI), and epithelial cell transforming 2 (ECT2) is detected in lung squamous cell carcinoma (LSCC) tissues; biologically, Fxr1 forms a complex with PRKCI and ECT2 to promote cell proliferation and invasion." (PMID 35565262, 2022). "PRKCI/SOX2 signaling promotes the Hedgehog pathway and sustains lung squamous cell cancer stemness." (PMID 33924966, 2021).
breast carcinoma (5 papers, 2016 to 2023). "And third, RNA-seq of neutrophils from breast cancer patients and controls identified the gene PRKCI to be overexpressed in patient neutrophils relative to neutrophils from cancer-free individuals." (PMID 28721376, 2016). "The mRNA relative expression of PRKCZ was significantly higher than PRKCI in breast cancer cells, including 4T1 cells and MDA-MB-231 cells, which indicating PKC-ζ may be activated by superoxide more easily than PKC-ι." (PMID 37029374, 2023). "Furthermore, TNF stimulated neutrophil cytotoxicity against breast cancer cell lines and induced PRKCI expression in the subset of samples that had low basal expression of this gene." (PMID 28721376, 2016).
prostate carcinoma (5 papers, 2011 to 2023). A carcinoma that arises from epithelial cells of the prostate gland. "For instance, previously studies have identified genetic variants rs546950, rs4955720 in PRKCI gene which are associated with the risk of prostate cancer in Han Chinese and Iranian populations." (PMID 37667176, 2023). "We found an association of two SNPs in the PRKCI gene, rs546950 and rs4955720, with a decreased risk of prostate cancer." (PMID 21373201, 2011). "In conclusion, we found an association with prostate cancer risk for two SNPs belonging to PRKCI, a gene which is frequently overexpressed in various cancers, including prostate cancer." (PMID 21373201, 2011). "In conclusion, we found an association with prostate cancer risk for two SNPs belonging to PRKCI, a gene which is frequently overexpressed in various neoplasms, including prostate cancer." (PMID 21373201, 2011). "In this report we found that two allelic variants of the PRKCI gene were associated at a study-wise significant level with a decreased risk of prostate cancer." (PMID 21373201, 2011). "In the joint analysis of first and second phase two SNPs of the PRKCI gene showed an association with risk of prostate cancer (ORallele = 0.85, 95% CI 0.78–0.94, p = 1.3×10−3 for rs546950 and ORallele = 0.84, 95% CI 0.76–0.93, p = 5.6×10−4 for rs4955720)." (PMID 21373201, 2011). "In the second phase SNP rs546950 in the PRKCI gene showed a statistically significant association with prostate cancer risk, at the conventional threshold of p<0.05 (p2df = 0.02)." (PMID 21373201, 2011). "A role of genetic variation in the PRKCI gene in prostate cancer aetiology is plausible given that atypical protein kinase C lambda/iota (aPKCλ/ι), encoded by the PRKCI gene, is a protein kinase C isozyme, which plays multifunctional roles in cellular maintenance and growth of epithelial cells." (PMID 21373201, 2011). "The circRNA protein kinase C-iota has been suggested to influence tumor development, and a study found this molecule triggers growth and metastasis in prostate cancer by downregulation of miR-24-3p." (PMID 35267449, 2022). "Numerous protein kinases including AKT1, MAPK1/ERK, RPS6KA1/RSK1, cAMP-activated protein kinase (PKA), PAK1, PRKCI/nPKC-iota, PRKCE/nPKC-epsilon and PIM1 were reported to phosphorylate BAD in prostate cancer cells." (PMID 33668112, 2021).
cervical cancer (4 papers, 2020 to 2025). A primary or metastatic malignant neoplasm involving the cervix. "In cervical cancer, PRKCI mediates radiosensitivity via the Hedgehog/GLI1 pathway 43, and Garcinone C inhibits the tumorigenic and invasive potential of CRC stem-like cells by targeting the Hedgehog/GLI1 signaling pathway." (PMID 40384864, 2025). "There are few reports of PRKCI and its role in the carcinogenic mechanisms of cervical cancer." (PMID 32993576, 2020). "The experimental results of this study showed that the expression of PRKCI in cervical cancer tissue was significantly higher than it was in CIN tissue, which may be related to the progression of CIN." (PMID 32993576, 2020). "PRKCI is in the Hippo signaling pathway, but the mechanism by which it leads to CIN and cervical cancer is unknown." (PMID 32993576, 2020).
esophageal squamous cell carcinoma (4 papers, 2022 to 2024). Esophageal squamous cell carcinoma (ESCC) is a type of esophageal carcinoma (EC) that can affect any part of the esophagus, but is usually located in the upper or middle third. "miR-3680-3p was shown to be sponged by circ-PRKCI to regulate AKT3 expression in esophageal squamous cell carcinoma." (PMID 36941990, 2023). "For example, circ-PRKCI could sponge miR-3680-3p to stimulate the migration and proliferation of esophageal squamous cell carcinoma cells." (PMID 36612120, 2022). "Circular protein kinase C iota (Circ-PRKCI) is a microRNA (miRNA) sponge, and it has been shown that Circ-PRKCI can participate in tumor progression by stimulating migration and proliferation of esophageal squamous cell carcinoma cells through sponging miR-3680-3p." (PMID 37942325, 2023).
glioma (4 papers, 2019 to 2024). A benign or malignant brain and spinal cord tumor that arises from glial cells (astrocytes, oligodendrocytes, ependymal cells). "Circular RNA PRKCI contributes to progression of glioma by repressing microRNA-545." (PMID 34520391, 2021).
laryngeal squamous cell carcinoma (4 papers, 2020 to 2024). A squamous cell carcinoma that arises from the larynx. "Some studies have pointed out that the Akt-mTOR signaling pathway, downstream of PRKCI, promotes the malignant progression of laryngeal squamous cell carcinoma and inhibits autophagy." (PMID 39015499, 2024).